XRCC3 (X-ray repair cross complementing 3)
Description:
Involved in the homologous recombination repair (HRR) pathway of double-stranded DNA, thought to repair chromosomal fragmentation, translocations and deletions. Part of the RAD51 paralog protein complex CX3 which acts in the BRCA1-BRCA2-dependent HR pathway. Upon DNA damage, CX3 acts downstream of RAD51 recruitment; the complex binds predominantly to the intersection of the four duplex arms of the Holliday junction (HJ) and to junctions of replication forks. Involved in HJ resolution and thus in processing HR intermediates late in the DNA repair process; the function may be linked to the CX3 complex and seems to involve GEN1 during mitotic cell cycle progression. Part of a PALB2-scaffolded HR complex containing BRCA2 and RAD51C and which is thought to play a role in DNA repair by HR. Plays a role in regulating mitochondrial DNA copy number under conditions of oxidative stress in the presence of RAD51 and RAD51C.
Synonyms: CMM6
Tractability: PROTAC: ubiquitination databases record sites on it.
Gene: Protein-coding gene on chromosome 14 (103,697,569 to 103,715,504, reverse strand). Ensembl gene ENSG00000126215.
Subcellular location: Nucleus; Cytoplasm; Cytoplasm, perinuclear region; Mitochondrion
Subcellular location (Human Protein Atlas): Nucleoplasm
Pathways (Reactome):
DNA Repair: HDR through Homologous Recombination (HRR); Homologous DNA Pairing and Strand Exchange; Resolution of D-loop Structures through Holliday Junction Intermediates; Resolution of D-loop Structures through Synthesis-Dependent Strand Annealing (SDSA)
Gene Ontology:
Molecular function: crossover junction DNA endonuclease activity; four-way junction DNA binding; protein binding; ATP binding; ATP-dependent DNA damage sensor activity; DNA binding
Biological process: DNA repair; double-strand break repair via homologous recombination; interstrand cross-link repair; positive regulation of mitotic cell cycle spindle assembly checkpoint; regulation of centrosome duplication; replication fork processing; resolution of mitotic recombination intermediates; t-circle formation; telomere maintenance via recombination; telomere maintenance via telomere trimming; DNA damage response; DNA recombination; telomeric loop disassembly
Cellular component: cytoplasm; mitochondrion; nuclear replication fork; nucleoplasm; nucleus; perinuclear region of cytoplasm; Rad51C-XRCC3 complex; replication fork; chromosome, telomeric region
Genetic constraint (gnomAD): Loss-of-function variants: 35 observed, 25.41 expected, observed/expected ratio (o/e) 1.38, 90% interval 1.05 to 1.8. The upper end of that interval is the gene's LOEUF score, 1.8, which puts it in group 6 of 6, group 1 being the genes least tolerant of losing a copy. Missense variants: 463 observed, 417.11 expected, observed/expected ratio (o/e) 1.11, 90% interval 1.03 to 1.2. Synonymous variants: 223 observed, 184.47 expected, observed/expected ratio (o/e) 1.21, 90% interval 1.08 to 1.35.
Homologues: Orthologues: macaque XRCC3 (97% identical), chimpanzee XRCC3 (97% identical), rabbit XRCC3 (77% identical), dog XRCC3 (76% identical), mouse Xrcc3 (73% identical), rat Xrcc3 (73% identical), pig XRCC3 (73% identical), guinea pig XRCC3 (72% identical), tropical clawed frog xrcc3 (56% identical), zebrafish xrcc3 (53% identical), Drosophila melanogaster spn-B (31% identical). Paralogues in human: RAD51B (27% identical), RAD51C (25% identical), RAD51D (23% identical), RAD51 (22% identical), DMC1 (21% identical), XRCC2 (13% identical).
Diseases named in the same sentence as XRCC3 in open-access papers:
XRCC3 is named in the same sentence as 89 diseases in open-access papers, as found by Europe PMC text mining. Sharing a sentence is not in itself a finding about the gene and the disease. The quoted sentences say what the papers report.
breast cancer (53 papers, 2009 to 2025). A primary or metastatic malignant neoplasm involving the breast. "Our findings indicated that the XRCC1 rs25487, XPG rs17655, XRCC3 rs861539, and hMSH2 rs4987188 were associated with breast cancer risk in the Tanzanian women." (PMID 35691022, 2023). "Studies showed that rs861539 variant of XRCC3 gene was significant associated with the onset of multiple malignancies, such as gynecological malignancies, oesophageal cancer, prostate cancer, breast cancer, etc." (PMID 37212185, 2023). "XRCC3 polymorphism has been linked to the risk of multiple cancers, such as breast cancer, thyroid cancer, melanoma skin cancer, and lung cancer." (PMID 35978646, 2022). "The analysis we conducted on XRCC3 Thr241Met polymorphism portrayed that, homozygote expression of 241Met allele (241Met/Met) was associated with 3 times increased risk of developing breast cancer." (PMID 35320970, 2022). "In the analysis of XRCC3 Thr241Met polymorphism, women with homozygote expression (Met/Met genotype) of 241Met allele had three times increased risk of breast cancer (OR = 2.77, 95% CI = 1.26–6.11; P = 0.009)." (PMID 35320970, 2022). "Apart from rare mutations, several common single nucleotide polymorphisms (SNPs) in various HRR genes, including NBN, RAD51, and XRCC3, were reported to affect DNA repair capacity and were previously associated with altered breast cancer risk." (PMID 36139526, 2022). "In our study, we investigated the relationship between breast cancer risk and genetic variations in DNA repair [XRCC3 Thr241Met and XRCC4 G(‐1394) T] and apoptosis [BAX G(-248) A and BCL-2 C(‐938) A] pathways." (PMID 35320970, 2022). "The risk of breast cancer was 2.77 times more in individuals carrying the Met/Met genotype of XRCC3 Thr241Met (rs861539) (P = 0.009)." (PMID 35320970, 2022). "We investigated the relationship between the risk of breast cancer and XRCC3 Thr241Met, XRCC4 G(-1394) T, BAX G(-248) A, and BCL2 C(-938) A gene polymorphisms." (PMID 35320970, 2022). "In that study having 241 Met/Met genotype in XRCC3 Thr241Met gene polymorphism was reported as a risk factor for breast cancer especially in the Asian population." (PMID 35320970, 2022). "L939W reduces interaction with BRCA2, RAD51, XRCC3 and decreases double stranded DNA break initiatedhomologous recombination associated with breast cancer susceptibility." (PMID 34092963, 2021). "This meta-analysis confirms that XRCC3 rs1799794 is related to cancer risk, especially increased risk for breast cancer and thyroid cancer and reduced risk for ovarian cancer." (PMID 33931047, 2021). "Observed genotype and haplotype frequencies together with respective odds ratios (ORs) and corresponding 95% confidence intervals for Xrcc3 polymorphisms in breast cancer cases and control subjects." (PMID 31905201, 2020). "In the hereby presented study we examined the role of genetic variability of two proteins belonging to the HR DSB DNA repair pathway—Rad51 and Xrcc3—as a risk factor for breast cancer in Polish population." (PMID 31905201, 2020). "The previous published data on the association between XRCC3 Thr241Met, A4541G, and A17893G polymorphisms and breast cancer risk remains largely controversial, and population related differences in association are reported frequently." (PMID 26881229, 2016). "On the other hand, of the polymorphisms investigated comparing breast cancer smokers and healthy smokers, statistically significant associations between two genetic variants and risk of breast cancer in smokers were observed (XRCC3 Met241, CYP1A1 Ile462)." (PMID 27754415, 2016). "In conclusion, the results obtained during this study suggest that rs1799794 in XRCC3 shows strong association with breast cancer development in Saudi females." (PMID 26881229, 2016).
breast cancer (continued). "We investigated three common polymorphisms (SNPs) in the XRCC3 gene (rs861539, rs1799794, and rs1799796) in 143 Saudi females suffering from breast cancer (median age = 51.4 years) and 145 age matched normal healthy controls." (PMID 26881229, 2016). "Evidence from meta-analysis supports a positive association between the XRCC3 p.Thr241Met polymorphism and the risk of bladder cancer, breast cancer, cervical cancer and hepatocellular carcinoma." (PMID 26091483, 2015). "In the Polish population, Thr241Met genotype of XRCC3 polymorphism increased the risk of breast cancer development." (PMID 24728564, 2015). "A meta-analysis has revealed that the XRCC3 gene rs861539 polymorphism also increases the risk of developing hepatocellular carcinoma, as well as head and neck, bladder, and breast cancer." (PMID 26339569, 2015). "In the reported study, the Arg188His polymorphism of XRCC2 gene and Thr241Met of XRCC3 were correlated with breast carcinoma progression." (PMID 24728564, 2015). "And a few meta-analyses have been conducted on XRCC3 C18067T polymorphism and cancers risk, including colorectal cancer, lung cancer, bladder cancer, and breast cancer." (PMID 24454720, 2014). "Numerous association studies have evaluated XRCC3 SNPs as candidate risk factors for breast cancer, but the results of these studies remain controversial." (PMID 24139550, 2013). "And epidemiological studies have demonstrated a correlation between gene polymorphisms of XRCC3 and breast cancer risk." (PMID 23977219, 2013). "The XRCC3 p.Arg150Cys variant was detected in a family with 1 ovarian cancer and 5 breast cancer cases." (PMID 24139550, 2013). "An association between wild type XRCC3 C18067 and an increased rate of late toxic effects, such as subcutaneous fibrosis, were found in breast cancer and prostate." (PMID 22272830, 2012). "Our results suggest that in addition to its' role in facilitating repair of DNA damage, XRCC3 affects invasiveness of breast cancer cell lines and the expression of genes associated with cell adhesion and invasion." (PMID 21283680, 2011). "These include Rad52, the human Rad51 paralogs Rad51B, Rad51C, Rad51D, Xrcc2, and Xrcc3, and breast cancer susceptibility gene Brca2." (PMID 21129202, 2010). "Meta-analysis of the XRCC3 T241M polymorphism on the risk of breast cancer." (PMID 36761956, 2023). "Amino acid substitution variants of XRCC1 and XRCC3 genes may contribute to breast cancer susceptibility." (PMID 35563727, 2022). "One of the most investigated SNP is XRCC3 rs861539, and several studies and meta-analyses suggest it may contribute to breast cancer risk." (PMID 36139526, 2022). "XRCC3 rs1799794 was also associated with increased breast cancer risk." (PMID 36139526, 2022). "It was shown that XRCC3 241Met allele carriers had increased risk of developing breast cancer." (PMID 35320970, 2022). "Similarly, XRCC3 has such a mutation pattern in multiple cancer types, including thyroid cancer and breast cancer." (PMID 34513841, 2021). "XRCC3 rs861539 polymorphism is associated with poor prognosis of breast cancer patients." (PMID 33931047, 2021). "Associations of Rad51/Xrcc3 SNP combinations with breast cancer." (PMID 31905201, 2020). "Besides, XRCC3 overexpression has been found to be associated with clinical factors in breast cancer." (PMID 32258128, 2020). "However, most subsequent studies on Caucasians failed to confirm this association, though a few studies did report that XRCC3 Thr241Met is related to an increased risk of breast cancer." (PMID 26881229, 2016). "Our results among Saudis suggest that some variations in XRCC3 may contribute to breast cancer susceptibility." (PMID 26881229, 2016). "All three genotypes were identified for each SNP and the results suggested that some variations in XRCC3 may contribute to breast cancer susceptibility." (PMID 26881229, 2016).
breast cancer (continued). "With this background we initiated this case-control study on Saudi breast cancer patients and investigated three commonly reported XRCC3 polymorphisms (Thr241Met c.722 (rs861539), c.562-14 (rs1799796), and c.316 (rs1799794)) in the patients in comparison with the healthy controls." (PMID 26881229, 2016). "Although the functional relevance of the XRCC3 Thr241Met variation is unknown, some studies have reported that this polymorphism is associated with increased risk of breast cancer." (PMID 26339569, 2015). "Although the functional relevance of XRCC3 Thr241Met variation is unknown, some studies have reported that the 722T/T genotype is associated with increased risk of breast cancer." (PMID 24728564, 2015). "A meta-analysis of 157 case-control studies reported the participation of XRCC3 T241M in the susceptibility for bladder and breast cancer, particularly in Caucasian individuals, and the XRCC3 T241M polymorphism was associated with a decreased risk of lung cancer." (PMID 25013509, 2014). "And T241M in XRCC3 may be associated with breast cancer risk, especially in the Asian population." (PMID 36761956, 2023). "The joint effect of RAD51 rs1801321 and XRCC3 rs861539 (HR pathway) on cancer risk has been previously reported for breast cancer, in line with our results, and may be of particular relevance for DTC since the formation of radiation damage-induced RAD51 foci requires functional XRCC3." (PMID 31374908, 2019). "In breast cancer, XRCC3 deletions were present in 0.3% of primary tumours (TCGA dataset) and in 2.1% of metastatic breast cancers." (PMID 37029129, 2023). "In the present study, we evaluated the association of tag SNPs in HRR genes NBN, RAD51 and XRCC3 with toxicity and outcome of adjuvant RT and tumor differentiation grade in early HER2-positive breast cancer patients." (PMID 36139526, 2022). "As a secondary aim, we evaluated the association of NBN, RAD51 and XRCC3 SNPs with tumor differentiation grade and occurrence of a new primary tumor after longer follow-up in patients with early HER2-positive breast cancer." (PMID 36139526, 2022). "Our study’s primary aim was to evaluate the association of common putatively functional SNPs in HRR genes NBN, RAD51, and XRCC3 with RT adverse events in patients with early HER2-positive breast cancer treated with adjuvant RT." (PMID 36139526, 2022). "A tendency for a decreased risk of breast cancer was observed with the occurrence of 188His/His genotype and 188His allele of XRCC2 and 241Met/Met genotype and 241Met allele of XRCC3 polymorphism." (PMID 24728564, 2015). "To evaluate the contribution of RAD51, XRCC3, and XRCC2 mutations to breast cancer predisposition, we screened 182 familial Finnish breast or ovarian cancer patients for germline variation in the RAD51 and XRCC3 genes and 342 patients for the XRCC2 gene." (PMID 25918678, 2015). "While germline mutations in RAD51C and RAD51D are associated with high ovarian cancer risk and RAD51B polymorphisms with breast cancer, the contribution of RAD51, XRCC3, and XRCC2 is more unclear." (PMID 25918678, 2015). "Taken together, it is unlikely that RAD51, XRCC3, and XRCC2 have a significant contribution to breast cancer susceptibility." (PMID 25918678, 2015). "Like most of the known breast cancer susceptibility genes, RAD51, XRCC3, and XRCC2 also have a role in DNA double-strand break repair by homologous recombination." (PMID 25918678, 2015). "The association of RAD51, XRCC3, and XRCC2 haplotypes with breast cancer risk was studied among 1516 breast cancer cases (including 592 familial cases) and 1234 population controls." (PMID 25918678, 2015). "In addition, the XRCC3 241M allele may act as a risk factor for breast cancer." (PMID 25013509, 2014). "We extracted seven genes, XRCC3, XRCC2, RAD51C, RAD51L1, RAD51L3, FANCG, BRCA2, that formed a connected PPI network with eight interactions, and had been associated with breast cancer as well as other types." (PMID 24784581, 2014).
breast cancer (continued). "We therefore in this study aimed to assess the potential interactions of seven common polymorphisms from five DNA repair genes (XRCC1, XRCC2, XRCC3, XPA and APEX1) in association with breast cancer among Han Chinese women." (PMID 24642895, 2014). "A recent meta-analysis suggested that the minor allele of XRCC3 p.Thr241Met SNP was a low risk factor and XRCC3 IVS5-14A > G SNP a low protective factor for breast cancer." (PMID 24139550, 2013). "It suggested that expressions for both XRCC3 and RAD51 were significantly higher in breast cancer (XRCC3: P<0.001; RAD51: P<0.001)." (PMID 23977219, 2013). "A total of 57 breast cancer patients who underwent SSPBI were genotyped for SNPs (single nucleotide polymorphisms) in XRCC1, XRCC3, GST and RAD51 by Pyrosequencing technology." (PMID 22272830, 2012). "Our results demonstrate that 2-3 fold increase in the expression of XRCC3 protein levels is sufficient to significantly increase the invasive behaviour of two human breast cancer cell lines (MCF-7 and BT20) in vitro." (PMID 21283680, 2011). "Our results demonstrate that stable or transient over-expression of XRCC3 increases in vitro invasiveness in two breast cancer cell lines from different lineage (luminal and triple negative)." (PMID 21283680, 2011). "Specifically, we over-expressed XRCC3 in two breast cancer cell lines, MCF-7 and BT20, with contrasting phenotypes and clinical prognosis." (PMID 21283680, 2011). "Genetic variability in DNA double-strand break repair genes such as RAD51 gene and its paralogs XRCC2、XRCC3 may contribute to the occurrence and progression of breast cancer." (PMID 36761956, 2023). "This study is aimed at determining the association of XRCC3 Thr241Met (rs861539), XRCC4 G(-1394) T (rs6869366) DNA repair and BAX G(-248) A (rs4645878), and BCL2 C(-938) A (rs2279115) apoptotic gene polymorphisms with breast cancer." (PMID 35320970, 2022). "The relationship between XRCC3 Thr241Met gene polymorphism and breast cancer was not studied previously." (PMID 35320970, 2022). "XRCC3 forms a functional complex (the CX3 complex) with another RAD51 paralog, RAD51C, whose LoF events are also mainly caused by gene silencing, in this case in breast cancer samples." (PMID 36969741, 2022). "In conclusion, XRCC3 and RAD51 polymorphisms might contribute to RT adverse events in early HER2-positive breast cancer patients." (PMID 36139526, 2022). "Even though data regarding the influence of genetic variability on the occurrence of a new tumor are scarce, there are many reports in the literature that DNA repair genes, including XRCC3 and RAD51, are associated with the development of breast cancer and other cancer types." (PMID 36139526, 2022). "Previously, XRCC2 p.(Arg188His) has been associated with poor breast cancer survival but in our study, no survival effect was found for this variant or for the XRCC3 p.(Thr241Met) variant." (PMID 25918678, 2015). "Similar to our observation, the recent reports demonstrate that XRCC3 Thr241Met allele seems associated with an elevated breast cancer risk in non-Chinese subjects." (PMID 24728564, 2015). "Taking the similarity and close association between XRCC3 and RAD51 into account, it is speculated that XRCC3 may also play an important role in the pathogenesis of breast cancer." (PMID 23977219, 2013). "XRCC3 and RAD51 were significantly associated with clinicopathological factors and they might play important roles in the development and progress of breast cancer." (PMID 23977219, 2013). "While few studies on XRCC3 expression in breast cancer were reported." (PMID 23977219, 2013). "The contribution of RAD51, XRCC3, and XRCC2 to breast cancer susceptibility remains unclear." (PMID 25918678, 2015).